NES (nestin)
Diseases named in the same sentence as NES in open-access papers (continued):
Sharing a sentence is not in itself a finding about the gene and the disease.
glioma (continued). "We next investigated whether Pax3 expression characterizes any Nestin-progenitors, the targeted cell-of-origin in our glioma mouse model, in the P3 mouse brainstem." (PMID 25330836, 2014). "All but one glioma utilized for insertion site cloning in our study were from Rosa26-SB11 mice in which transposase is expressed in most cells of the body, therefore it is possible that gliomas in Rosa26-SB11 mice arise from a different cell type than gliomas derived from Nestin+ cells." (PMID 25423036, 2014). "Thus the regional expression pattern of Pax3, and its co-expression with Nestin, in the neonatal mouse brain correlates with its expression in glioma." (PMID 25330836, 2014). "Nestin is an intermediate filament expressed by neuroepithelial progenitor cells and newly formed endothelial cells and can be re-expressed by mature cells, such as astrocytes in glial neoplasms, and in response to brain injury." (PMID 25051370, 2014). "The finding that therapeutic concentrations of melatonin (3 mM) were required to induce significant changes in the expression levels of Nestin in C6 glioma cells suggests differences between the cell lines; however, this result does not imply that glioma tissues are less responsive to melatonin." (PMID 24137328, 2013). "Thus, at least for gliomas, the identification of other CSCs markers, such as nestin, an intermediate filament, a marker of neural stem cells, or CD15 (SSEA1 or Lewis X) present in primary neurospheres, is under evaluation." (PMID 23476653, 2013). "Notch signalling can directly up-regulate nestin expression in gliomas." (PMID 23998913, 2013). "The targeting of VEGF using neutralizing mAb, bevacizumab was also effective at inhibiting tumour growth of xenografts derived from CD133+ glioma-initiating cells or U87 glioma cells by decreasing the number of self-renewing and vessel-associated CD133+/nestin+ tumour cells." (PMID 23301832, 2013). "The presence of nestin-positive stem or progenitor cells in and around glioma may have protective effects against glutamate cytotoxicity." (PMID 22539956, 2012). "In a study by Lee and colleagues, human fetal NSCs underwent tumorigenic transformation through the introduction of genes such as v-myc and H-Ras, which resulted in heterogeneous glial tumors with some characteristics of cancer stem cells (small numbers of nestin+ neural stem-like cells)." (PMID 22973309, 2012). "In addition, nestin expression correlates well with histological grade of glioma and clinical outcome." (PMID 22330721, 2012). "Nestin is a strong prognostic marker of glioma malignancy; the invasive cells may well be closely related to glioma stem cells, which our data confirms." (PMID 22995409, 2012). "This may suggest that glioma and/or the brain tissue surrounding the tumor secrete soluble factors that may stimulate the proliferation of nestin-positive host cells." (PMID 22539956, 2012). "Quantification of the tumor areas in sections of U251 glioma xenografts indicated that approximately 29% of the area contained cells that stained positive for human nestin and 8% was positive for host mouse nestin, whereas 63% was negative for both human and mouse nestin." (PMID 22539956, 2012). "This may suggest that glioma in the cerebral frontal lobe may exert ‘long-distance’ effects, which may lead to upregulation of nestin expression in the cerebellar vasculature." (PMID 22539956, 2012). "With the known correlation of increased nestin expression with higher-grade glioma, coupled with the known prognostic value of tumor grade alone in glioma, it is unclear if nestin expression would retain its prognostic value in these studies if tumor grade was considered independently." (PMID 18817556, 2008). "Interestingly, in many of these tumors, including glioma, nestin expression has been shown to correlate with advanced grade, supporting its application as a marker for dedifferentiation." (PMID 18817556, 2008).
glioma (continued). "Interestingly, these early studies identified higher levels of nestin expression in GBM than in lower grade gliomas, supporting its potential application as a marker for dedifferentiation in glioma." (PMID 18817556, 2008). "Greater than 90% of Nestin positive glioma cells were also c-Myc positive." (PMID 19020659, 2008). "As glioma-initiating stem cells are characterized by neural stem cell markers, e.g., nestin and CD133, downregulation of β-1,4-GalT-V was also accompanied by reduced mRNA expression of these neural stem cell markers, suggesting that CD133 and nestin may well have β-1-4 galactosylated epitope." (PMID 38203654, 2023). "We observed that in GEMM of gliomas, oncostreams are formed by GFP+ tumor cells, and are enriched in other tumor microenvironment cells such as ACTA2+ mesenchymal cells, IBA1+, and CD68+ tumor associated microglia/macrophages cells, Nestin+ cells and GFAP+ glial derived cells." (PMID 35750880, 2022). "Additionally, the quantification of nestin, a cell surface marker used as a biomarker for glioma stem cells, further revealed the presence and spreading of the tumor within these regions in the DIPG group, while no nestin was detected in the control group (data not shown)." (PMID 32349240, 2020). "Additionally, our functional data suggest the utility of high ALDH3A1 expression as a putative diagnostic marker for stemness in glioma as indicated by reduced expression of CD133, Nestin and Sox2 as well as diminished clonogenicity in response to ALDH3A1 inhibition." (PMID 29854309, 2018). "However, the prognostic role of CD133 and Nestin in gliomas still remains controversial." (PMID 25967234, 2015). "However, it is interesting to mention that in the same study, VPA an HDAC inhibitor was sufficient to drive down DNA methylation at the Nestin promoter in vitro in infected glioma cells, highlighting the closely interrelated impact of DNA methylation and histone modification." (PMID 25101247, 2014). "The transcription of Nestin, along with the transcription of two other genes that are important to nervous system development (Bmi-1 and Sox2), were used as markers of cell proliferation to evaluate the role of melatonin on glioma cell differentiation and proliferation." (PMID 24137328, 2013). "Because glioma pathology, invasion and angiogenesis are closely tied to the activity of various MMPs, and based on our current data, it is likely that recruitment of rat nestin-positive host cells by glioma reflects the intricate processes of glioma biology, including tumor hypoxia and angiogenesis." (PMID 22539956, 2012). "At 12 weeks highly invasive GFAP-/Nestin + high-grade astrocytomas develop, a progression that is accompanied by additional changes including overexpression of EGR, MDMT, loss of Pten and p16 and p19, all of which are known genetic markers associated with malignant human gliomas." (PMID 21896959, 2011). "Interestingly, upon knockdown of SOX2 the expression of the stem cell markers Nestin and Oct4 was decreased in U343-MG and U373-MG glioma cells supporting the view that SOX2 preserves a more undifferentiated cell phenotype as previously observed in neural stem cells." (PMID 22070920, 2011). "Statistically significant correlations between the percentages of immunostained cells and pathological grades of gliomas were found for Nestin (cp = 0.592, p < 0.01) and CD133 (cp = 0.563, p = 0.01), which means that with higher malignant grades of gliomas, higher protein expression could be found." (PMID 19108713, 2008). "Further studies evaluating nestin expression may be more informative when studied in lower grade glioma, in the context of markers more specific to tumor stem cells, and using more recent specimens from patients treated with temozolomide in conjunction with radiation." (PMID 18817556, 2008). "In addition, studies focused on nestin expression in low-grade glioma may also have more definitive clinical applications." (PMID 18817556, 2008).
glioma (continued). "Guggulsterone also reduced GSC stemness by decreasing the levels of nestin and IQGAP-1, markers of glioma stem cells." (PMID 40559213, 2025). "Ubiquitous activation of mutant Ppm1d was modeled using the Meox2-Cre driver, and primary gliomas were modeled using the RCAS/tv-a system to introduce Cre and PDGFB co-drivers into Nestin-positive neural stem cells." (PMID 41394550, 2025). "Another study found that arsenic trioxide inhibits the levels of Notch1 and Hes1 proteins, reduces nestin+ cells, and thus decreases the CSC populations in gliomas." (PMID 40799240, 2025). "Genes linked to stemness and therapy resistance included CD133 (PROM1), SOX2, Nestin, OLIG2, and Musashi-1, all of which support the persistence of glioma stem-like cell populations and drive recurrence." (PMID 41179304, 2025). "Clinically, we observed a significant inverse correlation between Sohlh1 and Nestin expression levels, and a positive correlation between Sohlh1 and SFRP1 expression in glioma tissues." (PMID 40418209, 2025). "At the same time, eckol was observed to reduce the expression of glioma stem cell markers such as CD133, nestin and Musashi-1, Sox2, Notch2, and β-catenin." (PMID 40559213, 2025). "The values of SOX2 across all steps suggest some stemness, either glioma stem cells or more likely tumor cells with stem cell phenotype considering low expression of SOX10 and NESTIN." (PMID 39230703, 2024). "Through the sponging of miR-145–5p, circPTN stimulated glioma stem cells to tumor sphere formation and stemness marker expression like CD133, Nestin, SOX2, and SOX9." (PMID 39170516, 2024). "By increasing Nestin, the oligodendroglial differentiation transcription factor SOX10, which was upregulated in gliomas, enhances the CSCs characteristic in breast cancer." (PMID 39170516, 2024). "In the context of glioma, several studies have highlighted the significance of glioma stem cell markers, specifically CD133 and Nestin, in determining the prognosis of gliomas patients." (PMID 38473403, 2024). "ZBTB42 is positively related to glioma stem cells marker genes such as CD44, MSI1, Fut4, and NES and the high expression group has a stronger relationship with glioma stemness." (PMID 36762114, 2023). "In a mouse glioma model, high-grade glioma was developed in connection with intratumoral macrophages infiltration, in which mice PDGFB was expressed under the control of glioneuronal-specific nestin promoter." (PMID 37790751, 2023). "Western blot further confirms that neural stem cell marker NESTIN and NR2E1 were highly enriched in mouse and human BTICs as compared to the glioma cell lines U251, T98G and LN229." (PMID 36321378, 2023). "Nestin-ΔTK-IRES-GFP transgenic mice were used to label resting CSCs and glioma tumor cells in a mouse glioma model." (PMID 37790807, 2023). "Paired samples from glioma patients were analyzed by immunohistochemistry for expression of the following stem cell markers: CD133, Musashi, Nanog, Nestin, octamer-binding transcription factor 4 (Oct4), and sex determining region Y-box 2 (Sox2)." (PMID 35183162, 2022). "Western blotting and immunostaining showed increase in molecular markers (GFAP, NeuF-H, β-tubulin-III, MAP2, Nestin, and GAP43) that confirmed the differentiation of glioma to astrocytes." (PMID 35011307, 2021). "Our study provided evidence suggesting that collagen and FN collaborate to facilitate proliferation and tumorigenesis of glioma cells through the PI3K/AKT/SOX2 and CDC42/F-actin/YAP-1/Nupr1/Nestin pro-survival signaling networks." (PMID 33408794, 2021). "Due to the specific up-regulation of nestin promoter in gliomas, rQNestin34.5v.2 vectors were designed within an insertion with a copy of RL1 gene under the transcriptional control of nestin promoter." (PMID 34055646, 2021).
glioma (continued). "Glioma stem cells, characterized by the expression of CD133 and nestin, represent a mainstay in the pathogenesis of treatment resistance and recurrences." (PMID 33799798, 2021). "The markers were glioma stem cell markers (CD133 and Msh1), neuronal lineage markers (nestin, sox1, sox2, and pax6), and differentiated markers (GFAP, Tuj1, and Olig123)." (PMID 33575478, 2021). "TMZ resulted in the increased expression of CD15, a marker which is downregulated in low grade gliomas, while it also altered the expression of CD24, CD44, and nestin." (PMID 33530325, 2021). "We provided evidence that collagen/FN complex regulates glioma stemness via an integrin αvβ3-activated PI3K/AKT/SOX2 and CDC42/F-actin/YAP-1/Nupr1/Nestin signaling network." (PMID 33408794, 2021). "We found that the glioma tissue was diffusively positive for GFAP, Nestin, slightly positive for Olig2, S-100; the positive rate of Ki-67 was 65% and negative for Vimentin." (PMID 33391433, 2021). "The involvement of Nestin in GBM and its use as a biomarker for glioma stem cells suggests a possible interaction of TOX3 in this cancer." (PMID 34298641, 2021). "Glioma cells in PpIX hotspots were IDH1 mutant and expressed nestin suggesting they had acquired stem-like properties." (PMID 33959713, 2021). "Treatment of the sphere-cultured glioma cells with eckol in concentrations from 50 to 90 μM also decreased the expression of the glioma stem-like cell markers CD133, Nestin, and Musashi-1." (PMID 34440090, 2021). "Circ_EPHB4 upregulates the expression of SRY-box transcription factor 10 (SOX10) and Nestin (NES) by directly sponging miR-637, thereby stimulating the stemness, proliferation, and glycolysis of glioma cells." (PMID 34829818, 2021). "Knockdown of HDAC1 resulted in a significant decrease in the expression of glioma master transcription factors SOX2 and OLIG2, stem cell marker NESTIN, and the receptor tyrosine kinase epidermal growth factor receptor (EGFR)." (PMID 34494550, 2021). "Compared to WHO grade II and grade III glioma, GBM had significantly higher expression of Nestin, STAT3, and CD133." (PMID 34638384, 2021). "To verify our data in vivo, we examined glioma tissues from patients and found elevated SOX2 and Nestin expression in high-grade malignant glioma tissues." (PMID 33408794, 2021). "In a mouse glioma model, a Nestin-∆TK-IRES-GFP transgenic mouse was created to label quiescent stem cells and glioma tumor cells." (PMID 32754274, 2020). "To better define the phenotypic characteristics of FAP+ cells in human glioma samples, we first used FAP/nestin and FAP/PDGFRβ double immunostaining on human glioma specimens." (PMID 33308315, 2020). "LGG85 cells grow as neurospheres, express nestin (NES), an intermediate filament specific for neural immature cells, as well as two transcription factors highly expressed in gliomas (OLIG2, SOX2)." (PMID 32218467, 2020). "Up-regulation of cathepsin B and uPA receptors induces SOX2 and Bmi1 expression, both critical for maintaining the stemness of glioma CSCs, while knockdown of cathepsin B and uPA receptors suppresses expression of SOX2, Bmi1 and nestin, in vivo." (PMID 31683669, 2019). "Hypoxia induced single differentiated CD133-/CD15-/NESTIN- glioma cells into viable neurospheres through elevated expression of critical genes including SOX-2, OCT-4, KLF-4, NANOG, CD133, CD15, NESTIN and ABCG2." (PMID 31835751, 2019). "Inhibition of the Notch signaling pathway also impedes the maintenance of glioma stem cells and tumorsphere formation, in addition to reducing the expression of the glioma stem cell markers CD133, SOX2 and nestin." (PMID 31683669, 2019). "Glioma CSCs as neural stem cells (NSCs), express stem cell markers such as CD133, SOX2, KLF4, and Nestin." (PMID 31661894, 2019).
glioma (continued). "Quantitative RT-PCR analysis showed decreased expression of Nanog, Sox2, KLF4, nestin and CD133, together with increased expression of the differentiation marker glial fibrillary acidic protein (GFAP) in AP-2α overexpressing glioma cells." (PMID 31534499, 2019). "Taken together, primary GBM cells in serum-containing medium differentiate, indicated by diminished nestin, increased GFAP intensity, and reduced expression of the putative glioma stem-cell markers, albeit with tumor and culture medium dependent variability." (PMID 29967607, 2018). "Immunostaining analysis of primary glioblastoma samples showed that cells overexpressing ALKB5 are characterized by the expression of the glioma stem cell markers SOX2, Nanog, Nestin, and OCT4; this stem cell phenotype is rescued by ALKBH5 expression." (PMID 30279357, 2018). "Expression of glioma stem-markers, such as CD133, Nestin, and Sox2 is significantly increased in tumours growing in suspension, as neurospheres." (PMID 29518912, 2018). "CD133+ C6 glioma cells were treated with STAT3 inhibitors WP1066 (5 μM) or S3 l-201 (50 μM) for 24 h and p-STAT3, STAT3, CD133, Nestin, SSES-1, and NANOG were measured using Western blotting analysis." (PMID 29284440, 2017). "We cultured CD133−CD15−NESTIN− glioma cells under hypoxia and detected the percentages of CD133, CD15 and NESTIN positive cells at days 0, 3, 6, 9, 12 and 15 with flow cytometry." (PMID 28427209, 2017). "Treatment with SI113, alone or in combination with EPO-A or VCR, yielded a modification of mRNA expression for OCT3/4, NANOG, NESTIN and OLIG2, all GBM or glioma stemness markers." (PMID 29340013, 2017). "Western blotting analysis showed that nestin, NANOG, and SSEA-1 were present in the CD133+ cells derived from C6 glioma cells." (PMID 29284440, 2017). "Immunocytochemistry (ICC) results indicated that the neural progenitor marker NESTIN, post-mitotic neuron marker TuJ 1, and glial cell marker GFAP were expressed in U87 glioma cells." (PMID 28837560, 2017). "Because CD133, Nanog, and Nestin are considered markers of glioma CSCs, we examined the gene and protein levels of CD133, Nanog, and Nestin in glioma CD133+ CSCs." (PMID 28881826, 2017). "In our study, we found that reduced LINC00461 expression reduced expression levels of some EMT markers (N-cadherin and ZEB1) and several other factors related to glioma “stemness” (CD44, SOX2, Nestin)." (PMID 29137410, 2017). "ShRNA targeting Notch ligand Delta-like 1 (DLL1) decreased CD133 and Nestin expression, and impaired the self-renewal ability of CD133+ U87-MG and U251-MG glioma cells, indicating DLL1/Notch1 signaling promoted stem cell phenotype maintenance." (PMID 28380416, 2017). "Our results from the analysis of tumor tissues from patients with malignant gliomas have demonstrated preferential expression of IL-17R in glioma cells which also expressed GSC markers CD133, Nestin, and Sox2." (PMID 26755664, 2016). "To test this we performed qPCR on a selected panel of mRNAs of importance in glioma stem cell function: CD133, nestin, vimentin, TUJ1, GFAP and MAP2." (PMID 27564115, 2016). "We found that the glioma stem cell marker CD133, SOX2 and Nestin were reduced following combination treatments and NOTCH inhibitors albeit in a different manner." (PMID 27183910, 2016). "The expression of glioma stem cell marker CD133 was reduced after single or combined treatments with NOTCH inhibitors, whereas the triple combination also decreased SOX2 and Nestin expression." (PMID 27183910, 2016). "In A2B5+ /CD133− SHG-139S glioma stem like cell spheres, the percentages of positive cells for IDH1R132H (C1), Nestin (C3), NG2 (C4) and Vimentin (C5) were respectively 36.77 ± 13.19%,73.86 ± 5.01%, 49.12 ± 12.83% and 73.37 ± 2.09%." (PMID 25879429, 2015). "These cells express nestin, vimentin, and SOX2 and show malignant orthotopic tumor growth, indicating that EGFRamp is serially-maintained in the glioma stem-cell-like subpopulation." (PMID 26381735, 2015).